TLR4 (toll like receptor 4)
Diseases named in the same sentence as TLR4 in open-access papers (continued):
Sharing a sentence is not in itself a finding about the gene and the disease.
infection (continued). "Third, we measured expression of TLR-2, TLR-4, and HLA-DR because these receptors are integral components of the host response to infection and are involved in activating the inflammatory and coagulant response to infection." (PMID 21085465, 2010). "However, an influence of infection type was observed in the remaining subgroups (TLR4, TIRAP/Mal heterozygous and wild type-patients)." (PMID 20525286, 2010). "In the preterm infants this may represent an appropriate response to RSV infection with increased degradation and utilisation of TLR4-dependent pathways to help clear the infection, or these findings may reflect the immunological immaturity of these infants." (PMID 19497921, 2009). "The expression of TLR4 may have important implications for inflammation and infection in response to pathogens." (PMID 19960069, 2009). "Using a non-malignant human cholangiocyte cell line (H69) that expresses multiple TLRs including TLR4, we previously demonstrated that infection of human cholangiocytes by C. parvum in vitro mimics parasitial apical invasion and TLR4/NF-κB-dependent epithelial responses in vivo." (PMID 19997496, 2009). "Using a mouse model of infection, we determined that co-inoculation of B. parapertussis with a TLR4 stimulant led to enhanced pro-inflammatory cytokine production and leukocyte accumulation as well as more efficient control and rapid antibody-mediated clearance of the bacteria." (PMID 19169359, 2009). "All of these changes were alleviated by intravenous infection with TLR4-shRNA lentivirus." (PMID 20017955, 2009). "As only the expression of TLR4 and not of other TLRs is markedly reduced in the main infiltrating inflammatory cell during active infection, this suggests both a specific effect on TLR4 expression and that neutrophils and TLR4 play an important role in host defence against RSV infection." (PMID 19497921, 2009). "Similarly, co-inoculation of B. parapertussis with a TLR4 agonist resulted in an attenuated course of infection." (PMID 19169359, 2009). "Indeed, different effects of TLR2 and TLR4 were found in both infection models as in tissue injury models." (PMID 18974879, 2008). "Similarly, bioluminescence in the chests of TLR4 mutant mice was significantly increased over the controls (p<0.05) on days 3–7 and 10 post-infection." (PMID 18802464, 2008). "Moreover, histological examination of infected lungs showed that TLR4 mutant mice had significantly more foci of inflammation in their lungs than did controls as early as day 3 post-infection." (PMID 18802464, 2008). "On day 3 post-infection, the beginning of the interval when increased levels of virus could be discerned in lungs of TLR4 mutant mice, C3H/HeJ TLR4 mutant mice had significantly more foci of inflammation than controls (p<0.05)." (PMID 18802464, 2008). "Modulation of TLR4 in respiratory epithelium may have important implications for airway inflammation and infection in response to inhaled pathogens." (PMID 18034897, 2007). "In order to study the extent and kinetics of the inflammatory response, we sacrificed WT, TLR2 KO, and TLR4 KO mice at multiple time points after infection and measured the concentrations of the proinflammatory cytokines TNFα and IL6 and the anti-inflammatory cytokine IL10 in lung homogenates." (PMID 17676990, 2007). "To further evaluate the role of TLR2 and TLR4 in the systemic inflammatory response after infection with B. pseudomallei, we semiquantitatively scored spleen histology slides generated from infected mice and performed routine clinical chemistry to evaluate hepatic and renal injury." (PMID 17676990, 2007). "It is hypothesized that through this expression pattern TLR4 modulates immunological tolerance in the lower genital tract and induces host defence against ascending infection in the upper genital tract." (PMID 16368002, 2005).
infection (continued). "Similarly, immunofluorescent analysis revealed high Caspase‐3 and TLR4 expression in the infection group, whereas these markers were significantly downregulated in the treatment groups, highlighting the potential anti‐inflammatory and cytoprotective effects of combination therapy." (PMID 41268882, 2025). "These different infection routes could lead to distinct patterns of bacterial dissemination, immune cell recruitment, and inflammatory responses, ultimately resulting in different roles for TLR4 in disease progression." (PMID 40821830, 2025). "However, all WT mice succumbed to infection by day 4, whereas all tlr4 mutant mice survived." (PMID 40817088, 2025). "In addition to TLR2 involvement, TLR4 involvement was also observed during the infection." (PMID 39729468, 2024). "It should be noted that the C3H/HeJ strain has a mutation at Toll Like Receptor 4 that leaves the mice susceptible to infection from gram-negative bacteria, though this would have minimal impact as cancer effects on health differ to those due to bacterial infection." (PMID 39208033, 2024). "Furthermore, gene expression of TNF-α, IL-1β, IL-6, and IL-8 were also significantly upregulated 1 to 5 h after infection by K. pneumoniae, although SeMet reduced inflammation and protein expression of TLR4, Ikappa-B, NF-κB, and TNF-α in bMECs and macrophages infected with ESBL E. coli." (PMID 39456758, 2024). "Moreover, it is also known that TLR4 is expressed in normal tissue, and it is widely recognized that in normal conditions, renal TLR4 expression is low; however, the expression of this molecule increases in response to renal injury and/or infection." (PMID 39640496, 2024). "In addition, it should be noted that some primed mice demonstrated NP-Ab titers before infection; as LPS can activate TLR4 on B cells and stimulate plasmablast differentiation, some Ab production upon peptide priming is possible, thus enhancing the total NP response." (PMID 37711622, 2023). "In addition, the flow cytometry data showed that the surface expression of TLR4 was reduced upon infection in a significant manner [from 45.33 ± 1.805% to 23.03 ± 2.266%] and it was further decreased nonsignificantly [18.2 ± 0.76%] in presence of TAK-242 treatment." (PMID 37153546, 2023). "In addition, Li and Zhang found that miR-708-5p influenced M. tuberculosis viability and the human macrophage inflammatory response during infection by targeting TLR4 and miR-708-5p mimics reduced proinflammatory factors including IFN-γ, interleukin-6 (IL-6), IL-1β, and TNF-α." (PMID 36912627, 2023). "Furthermore, the proposed vaccine’s high affinity for the innate immune receptor (TLR4) indicates that it could be able to stimulate both innate and adaptive immunity against pathogen infection." (PMID 37220125, 2023). "It was suggested by the lowest energy score of 937.6 for a molecular docking between the peptide vaccine and virus glycoprotein binding convenient receptor of TLR4 that the vaccine could have infection-inhibiting activity and might interact tightly with TLR4 receptor." (PMID 35399010, 2022). "After the Aeromonas infection, the transcriptional level of TLR4 gene encoding TLR4 showed significant differences (p < 0.05) in comparison with the expression of this gene in the non-infected cells, but this only occurred after infection with A. dhakensis, A. caviae, and A. veronii." (PMID 35874671, 2022). "The data engendered in this study indicate the importance of the main TLR4 (LPS) linker for SNP rs4986790 and infectious agents, since the most associated and studied infectious diseases were infections by Gram-negative bacteria, mediated by LPS, even with nonsignificant association here." (PMID 36506333, 2022).
infection (continued). "In vitro M1 macrophages are polarized through the engagement of Toll-like receptor 4 (TLR4) by pathogen-associated molecular patterns, such as lipopolysaccharide derived from infection with Gram-negative bacteria or other receptors, e.g., by stimulation with IFN-γ." (PMID 35499077, 2022). "However, we had not explored infection in B6 mice that are susceptible (cornea perforates) to infection despite the presence of TLR4." (PMID 36422579, 2022). "Therefore, it has been suggested that bacterial CL molecules might influence the host-Tlr4 response to infection." (PMID 35638781, 2022). "Furthermore, infection of human cells with L. braziliensis increased the production of TNFα and IL-10 in a TLR4-dependent manner, reinforcing the role of TLR4 as an important receptor in Leishmania infections." (PMID 35402314, 2022). "However, a study demonstrated that the TLR4 signaling pathway was activated in Pregnane X Receptor (PXR) deficient mice after L. monocytogenes infection, and the inflammation induced by TLR4 signaling was detrimental to host defense against the infection." (PMID 35269881, 2022). "TLR4 overexpression in monocytes enhances their internalization and killing of bacteria via caveolae-dependent endocytosis and promotes their ability to fight against pathogens during the earlier stages of infection; these are the first results from a large animal model." (PMID 33966642, 2021). "Therefore, activation of TLR4 during L.donovani-infection may depend on two regulatory molecules (Neu1 and siglec-E) both of which identify the sialic acids on TLR4 as their target." (PMID 33763070, 2021). "Supporting this hypothesis, we demonstrated siglec-E engages hypersialylated TLR4 during infection." (PMID 33763070, 2021). "To investigate whether A. muciniphila can inhibit the expression of TLR-2 and TLR-4 in LX-2 cells, we coinfected live and pasteurized A. muciniphila with three different multiplicities of infection (MOIs 1, 10, and 100) and EVs in various concentrations (1, 10, and 50 μg/ml) for 24 h." (PMID 34549998, 2021). "BALB/c mice, M. fortis, Toll-like receptor 4 (TLR4)-deficient mice and wild-type mice (C57BL/6) were infected with S. japonicum, and differences in miR-181a expression between BALB/c mice and M. fortis over different time points post-infection (0, 3, 7, 10 and 14 dpi) were compared." (PMID 34689797, 2021). "As TLR4 may be activated via PAMPs, DAMPs or XAMPs, we did an additional analysis of our data to further see if we had any indication of an ongoing LPS-driven low-grade infection." (PMID 34226490, 2021). "Thus, blocking the activation of the Tlr4-MyD88 signaling pathway may be an interesting approach to prevent infection-induced pathology at EBISs." (PMID 34360700, 2021). "The present study found that TLR4-defective C3H/HeJ mice infected with C. perfringens have a remarkably lower survival rate, an increase in viable bacterial counts, and accelerated destruction of myofibrils at the infection site compared with wild-type C3H/HeN mice." (PMID 33763386, 2021). "Furthermore, the mRNA expression levels of toll-like receptor 4 (TLR4), and nuclear factor kappa-B (NF-κB) were strikingly increased after infection with Aeromonas hydrophila (P < 0.05), while the TLR4 was strikingly decreased with alpha-ketoglutarate supplementation (P < 0.05)." (PMID 34220849, 2021). "However, animals that received LPS showed substantial TLR4 expression 2 days after infection." (PMID 35046936, 2021). "However, it has been shown that preterm infants carrying the allele TLR4-rs2737190-G are prone to infections by Gram-negative bacteria." (PMID 33138336, 2020). "In the event of infection, TLR4 inhibitors could be administered together with antibiotics." (PMID 32313651, 2020). "Moreover, we cannot exclude the possibility that TRIF could be induced later, or by TLR2 activation by lipoproteins upon infection, as illustrated by the Leptospira-induced production of NO in C3H/HeJ TLR4-defective mice." (PMID 32790743, 2020).
infection (continued). "Similarly, a prospective Greece study on intensive care unit (ICU)-acquired infections and their clinical outcomes found an association of TLR4 (D299G and/or T399I) and TLR9-T1237C polymorphisms with increased susceptibility to specific ICU-acquired infections, such as MDR A. baumannii." (PMID 33042864, 2020). "Mouse models of HSV-1 infections of the central nervous system have shown that TLR4 is not activated during infection; however, TLR4 knockout mice are more susceptible to ocular HSV-1 lesion development, suggesting it may play a role." (PMID 32708188, 2020). "To find out if replacing murine TLR4 with human TLR4 affects inflammation of the kidney after infection with L. interrogans, we analyzed the differences in histopathology and inflammatory markers in tissue collected from infected and uninfected mice two weeks post infection." (PMID 33519799, 2020). "This somewhat altered TLR4 response could explain the dissemination and kidney colonization after Leptospira infection in mice and it can provide a clue about the lack of profound differences between huTLR4 and WT mice after infection." (PMID 33519799, 2020). "However, neither TLR-2−/− nor TLR-4−/− mice were more susceptible to infection, in contrast to the poor cytokine responses of peritoneal macrophages to spherules from TLR-2−/− mice." (PMID 32545735, 2020). "One of the factors that could modify H. pylori infection is genetic predisposition; single nucleotide polymorphisms (SNPs) in TLR genes, such as TLR1, TLR2, TLR4 and TLR10, were shown to alter the bacterial binding, thereby modulating the risk of infection and subsequent cancer." (PMID 30641993, 2019). "However, complete inhibition of TLR4 may impose deleterious effect on the immunocompromised state of septic patients who succumb to secondary infection." (PMID 30814582, 2019). "Taken together our study ascertains the important role of enhanced cell surface Neu1 in TLR4 activation which has the potential to clear the parasite burden by generating a robust Th1 proinflammatory defense in the host cells which is otherwise reversed during infection." (PMID 31649671, 2019). "Also, TLR4 signaling pathway activation is essential in response to LPS infection." (PMID 30915370, 2019). "However, the key player involved in TLR4 inhibition by Neu1 during this parasite-infection is largely unknown." (PMID 31649671, 2019). "Additionally, the results of western blot test further demonstrated that LEP and DPEP significantly inhibited the high protein expression of TLR4, TLR7, MyD88 and NF-κB p65 caused by influenza A virus infection, and the inhibitory effect was more obvious on the 3rd day of infection." (PMID 31551774, 2019). "While influenza virus does not express TLR4 pathogen-associated molecular patterns (PAMPs), infection elicits increased levels of a host-derived damage-associated molecular pattern (DAMP), high-mobility-group box 1 (HMGB1), shown previously to be a TLR4 agonist." (PMID 31064834, 2019). "It is thus feasible that monocyte-derived macrophages and moDCs in L. major Δisp2/3 infection could be increased further as a result of TLR4-induced differentiation of monocytes, possibly via the absence of ISP2-mediated inhibition of serine peptidase activity." (PMID 29097502, 2018). "Mutation of TLR4 has been shown to result in susceptibility to infection by Gram-negative bacteria." (PMID 29928275, 2018). "Given that PD patients are prone to infections, this ability of sTLR2 would be advantageous when comparing with complete TLR blockade-based therapies, e.g., by combination of anti-TLR2 and -TLR4 antibodies, as these may have a detrimental effect on infection clearance." (PMID 30538643, 2018). "Since NK cells rarely express Dectin-1, TLR2, or TLR4 on their surface these experiments supported our hypothesis that DCs have a substantial supporting role in NK cell activation which may also play a role in vivo during infection with A. fumigatus." (PMID 30177958, 2018).
infection (continued). "Interestingly, both TLR4 and C23 protein levels were down-regulated beginning 4 h pi (late stage of infection), suggesting that these two receptors may participate in the early recognition and modulation of viral entry into N2a cells." (PMID 29427996, 2018). "P. berghei NK65 infection in Tlr4- and Ifnar1-deficient nonpregnant females." (PMID 29440369, 2018). "Thus, WT, RAGE deficient, TLR4 deficient and RAGE/TLR4 deficient mice were inoculated with PVM at seven days of age and later re-infected with mock or PVM 42fi days after the primary infection." (PMID 28099113, 2017). "In addition, infection of mice doubly deficient in TLR4 and IFNAR with a lethal dose of DENV2 did not result in significant differences in morbidity or mortality compared to IFNAR-deficient mice." (PMID 29121099, 2017). "Adult C57BL/6 mice deficient for toll-like receptor 4 (TLR4) or myeloid differentiation factor 88 (MyD88), μMT mice devoid of B cells as well as C57BL/6 mice deficient for the decay-accelerating factor (DAF)-1ko, were shown to die after infection with L. interrogans serovar Copenhageni." (PMID 28270811, 2017). "While the specific viral factor(s) that transiently upregulates HO-1 to facilitate CO-mediated suppression of the TLR4 pathway remains to be identified, our data predict that a virion component is responsible, thereby allowing the inhibition of innate host defenses immediately upon infection." (PMID 28421060, 2017). "However, non-TNFα-related mechanisms (e.g. through IL1β, TLR4 etc.)could still be able to control progress of the infection, and the net result is decreased pathogenicity." (PMID 27663205, 2016). "Therefore, the change in TLR4 induced by these polymorphisms does not seem to modify the course of the infection with HBV and HCV with regard to the TLR4-mediated immune response, at least in the groups analyzed in the present study." (PMID 26347404, 2015). "At 15 months post infection, strong positive correlation was revealed when parasite densities were correlated with FoxP3 transcription in both liver and skin (rs = 0.821, p = 0.023 and rs = 0.860, p = 0.019, respectively) and also TLR4 transcription in the lymph node (rs = 0.821, p = 0.023)." (PMID 26465878, 2015). "The binding of RSV F protein to TLR-4 on neutrophils could induce the massive production of NETs, which can fill the lungs and impair lung function and consequently aggravate the inflammatory symptoms of the infection in young children and babies." (PMID 25856628, 2015). "Among many up-stream signaling proteins involved in NF-κB activation, TLR4 plays a critical role and it is well-documented that TLR4/NF-κB pathway has a pivotal role in the pathogenesis of several intestinal inflammatory diseases and infection-induced tissue damage." (PMID 25228903, 2014). "However, transgenic Tie2 driven expression of TLR4 in Tlr4−/− mice, resulting in mice with TLR4 expression restricted to endothelial cells, was sufficient for adequate bacterial clearance after intraperitoneal infection with Escherichia coli." (PMID 25254554, 2014). "This contrasting regulation of JE by TLR3 and TLR4 molecules was more apparent (p = 0.0314 for TLR3 and p = 0.0342 for TLR4), when we evaluated the susceptibility of TLR3−/− and TLR4−/− mice to neuroinflammatory diseases after infection with a higher dose of JEV (2.8×107 pfu)." (PMID 25188232, 2014). "Recently, transgenic mice expressing human rather than mouse TLR4/MD-2 have been generated to test whether the blunted recognition of hypo-acylated LPS by the human receptor complex dictates susceptibility to infection of Y. pestis." (PMID 23745121, 2013). "bakeri infection leads to the atypical production of immunosuppressive TGF-β by intestinal CD4+ T cells in response to TLR-4 triggering by LPS poses the question whether such mechanisms of immune modulation help to avoid undesired immune activation by microbiota changes resulting from the infection." (PMID 24040152, 2013).